CFH (complement factor H)
Diseases named in the same sentence as CFH in open-access papers (continued):
Sharing a sentence is not in itself a finding about the gene and the disease.
end-stage renal disease (11 papers, 2006 to 2025). "One patient, with late diagnosis of CFH-ab and additional genetic risk factors who was treated only with PE and plasma substitution, reached end-stage renal disease and was later successfully transplanted using eculizumab prophylaxis." (PMID 37762692, 2023). "In aHUS, mutations and the presence of anti-CFH autoantibodies (AAbs) have been reported as plausible causes of CFH dysfunction, and it is known that CFH-related aHUS carries a high probability of end-stage renal disease." (PMID 35452676, 2022). "Paradoxically to most available data, our case features acute aHUS due to a CFH mutation with late onset (38-year-old) and rapid progression to end-stage renal disease." (PMID 24558625, 2013). "As CFH is a plasma protein produced mainly by the liver, kidney transplantation in patients with aHUS with CFH mutations who have progressed to end-stage renal disease is associated with 80% of graft loss due to disease recurrence." (PMID 17076562, 2006). "Although CFH, CFI, C3, and other complement-related factors have been reported pathogenic, CFH has the strongest impact on the pathogenesis of aHUS because CFH-associated aHUS carries a high probability of loss of renal function or end-stage renal disease (70–80%)." (PMID 35452676, 2022). "Although aHUS secondary to a genetic mutation is relatively rare, when occurring due to a mutation in Factor H (CFH), it usually presents with younger onset and has a more severe course, which in the majority ends with end-stage renal failure." (PMID 24558625, 2013). "The R161W variant in C3 causes hyperactive C3 convertase activity; this change increased the binding of C3b to factor B and reduced the binding of C3b to CFH and MCP, and resulted in a rapid progression to end stage renal failure." (PMID 25188723, 2014).
glomerulonephritis (11 papers, 2009 to 2024). A renal disorder characterized by damage in the glomeruli. "This is in contrast to the effect of CFH deficiency, which results in the development of glomerulonephritis in CFH knockout mice due to uncontrolled C3 activation." (PMID 21637784, 2011). "Factor H (CFH)-deficient (Cfh−/−) mice spontaneously develop C3 deposition along the glomerular basement membrane (GBM) with subsequent development of glomerulonephritis with features of DDD, a lesion dependent on C3 activation." (PMID 19411110, 2009). "Moreover, pigs with a genetic deficiency of CFH spontaneously developed glomerulonephritis before birth, resembling MPGN type II." (PMID 39309006, 2024). "Thus, CFH deficiency promotes B cell autoimmunity and this precedes chronic inflammation and the development of glomerulonephritis in Cfh−/− mice." (PMID 31354740, 2019). "In conclusion, glomerulonephritis diseases, particularly those that coexist with isolated C3 glomerulonephritis and aHUS, may be associated with CFH, complement factor I, and MCP mutations." (PMID 27460033, 2016). "Previous studies using a CSS model of IC-mediated glomerulonephritis concluded that podocyte-derived CFH was involved in the processing of both subendothelial and subepithelial IC deposits." (PMID 31133737, 2019). "In the mouse model of IC-mediated glomerulonephritis induced by chronic serum sickness (CSS), podocytes expressed CFH and facilitated the removal of glomerular ICs in both the subepithelial and subendothelial areas, and seemed to be the functional surrogate for human CR110." (PMID 31133737, 2019).
acute kidney injury (9 papers, 2014 to 2026). Sudden and sustained deterioration of the kidney function characterized by decreased glomerular filtration rate, increased serum creatinine or oliguria. "Mutations leading to aHUS occur mostly in the C-terminal SCR-19/20 domains of CFH, and aHUS is a common cause of renal failure in young children." (PMID 24744754, 2014). "Evaluation revealed thrombocytopenia, hemolytic anemia, and acute kidney injury with low C3, normal C4 & ADAMTS13 activity and positive anti-complement factor H antibody." (PMID 40443860, 2025).
glomerular disease (9 papers, 2012 to 2024). "Indeed, previous studies have implicated glomerular endothelial CFD and CFH in the pathogenesis of glomerular diseases." (PMID 39309006, 2024). "This dysregulation of the complement system caused by a long-term C5 inhibition is typically observed in patients with glomerular disease, who develop C3-associated deposits in the kidney comparable to those developed by patients with deficiencies in CFH and CFI28,43." (PMID 34001980, 2021). "In mice deficient in the complement factor H (CFH), a model of non-sclerotic and nonimmune-complex glomerular disease, IgM was identified as binding to glomerular epitopes and contributing to the progression of glomerular damage." (PMID 34876020, 2021). "They developed glomerulopathies at the age >50 and had no history of other diseases, despite the presence of anti-nuclear autoantibodies and risk haplotypes in other complement genes (MCP, CFH)." (PMID 35267578, 2022). "CFH−/− mice is an animal model of non-sclerotic and nonimmune-complex glomerular disease." (PMID 34876020, 2021).
preeclampsia (9 papers, 2011 to 2025). Preeclampsia is a hypertensive disorder of pregnancy that is characterized by new-onset hypertension with proteinuria presenting after 20 weeks of gestation, and depending on mild or severe forms may initially present with severe headache, visual disturbances, and hyperreflexia. "Of five deleterious genetic variants that were identified in seven pregnant women suffering from preeclampsia, one was associated with the gene of CFH (rs35274867), linked with the occurrence of preeclampsia." (PMID 40724958, 2025). "Gene-based burden testing for rare and unique variants (minor allele frequency <1%) in the FINNPEC cohort identified five heterozygous rare variants in CFH (L3V, R127H, R166Q, C1077S and N1176K) in 7 women with severe preeclampsia." (PMID 40777009, 2025). "We sequenced genes encoding three complement regulatory proteins—membrane cofactor protein (MCP), complement factor I (CFI), and complement factor H (CFH)—in 40 patients who had preeclampsia and found heterozygous mutations in seven (18%)." (PMID 21445332, 2011). "In this case one single mutation in CFH probably explains the entire phenotype (AMD, preeclampsia, hemolysis and altered renal function)." (PMID 32641076, 2020). "We identified heterozygous mutations in complement system pathway genes in seven of 40 patients with preeclampsia (18%)—four patients with mutations in MCP, two with CFI mutations, and one with a CFH mutation." (PMID 21445332, 2011). "All patients with preeclampsia were screened for mutations in the genes encoding the complement regulatory proteins MCP, CFI, and CFH." (PMID 21445332, 2011). "Furthermore, the investigation identified a number of genetic variants in the genes of ADAMTS13, C3, CFH, CFB, thrombomodulin, MBL2, and MASP2 that were significantly linked with the occurrence of preeclampsia, according to the results of analyses A and B." (PMID 38673014, 2024). "Notably, proteins linked to hematological and immune pathways were highlighted: C4b-binding protein alpha chain (C4BPA) and complement factor H (CFH), both acting as activators of complement pathways, with elevated levels observed in pregnancy-related conditions, such as preeclampsia." (PMID 40430124, 2025).
retinal degeneration (9 papers, 2013 to 2025). Degeneration of the retina. "As a known target of both miRNAs, and a key molecule associated with retinal degeneration, the regulation of CFH was confirmed using a luciferase assay." (PMID 33037565, 2021). "At the genetic level, mutations in genes such as complement factor H (CFH) and age-related maculopathy susceptibility 2 (ARMS2) have been identified as key risk factors for retinal degeneration, particularly in the context of AMD." (PMID 40428167, 2025). "The development of AMD is associated with CFH (an inhibitor for alternative complement), EFEMP1 (a high-risk gene for AMD and other retinal degenerations), and VEGFA (a protein associated with increased choroidal neovascularization)." (PMID 36078063, 2022). "Q-PCR analyses showed J cybrids had decreased expressions for CFH, C3, and EFEMP1 genes, high risk genes for AMD, and higher expression for MYO7A, a gene associated with retinal degeneration in Usher type IB syndrome." (PMID 23365660, 2013).
glaucoma (8 papers, 2013 to 2024). Increased pressure in the eyeball due to obstruction of the outflow of aqueous humor. "Additionally, oxidative stress, another risk factor for glaucoma, downregulated the expression of the alternative pathway component CFH in rat retinal cells." (PMID 38396986, 2024). "For example, if the Y402H variation in complement factor H was a risk allele for both glaucoma and AMD, the likelihood for identification of this variation as a risk allele for either disorder would be diminished compared to studies using normal controls (patients with neither glaucoma or AMD)." (PMID 23536807, 2013). "For instance, research by Tezel and colleagues in 2010 revealed that CFH, an inhibitor of the alternative complement pathway, is reduced in patients with glaucoma." (PMID 38396986, 2024). "They noted that a five protein-panel, amongst others this included complement factor H, as another component of the alternative pathway, predicted the transition to glaucoma in about 78% of these animals." (PMID 34867198, 2021). "Earlier studies have shown that immune-related proteins and several members of the complement components including C1S, C1r, C7-C9, and CFH are activated in glaucoma." (PMID 33808966, 2021). "In the current study, the previously reported AMD associations, CFH and ARMS2, were readily detected as AMD associated loci using the glaucoma cohort as the control, with allele frequencies similar to those reported in other studies." (PMID 23536807, 2013). "A trend toward downregulation of complement factor H (CFH) was reported in patients with glaucoma." (PMID 39104531, 2024). "The observed reduction in CFH levels in the retina of glaucoma patients aligns with our findings and may suggest a potential AH biomarker for elevated oxidative stress and POAG." (PMID 37763167, 2023). "Moreover, the five-protein panel consisting of complement C4a, complement factor H, ficolin-3, apolipoprotein A4, and transthyretin predicted the transition to glaucoma in 78% of cases, and to the advanced disease in 89%." (PMID 32585848, 2020). "This downregulation of CFH was observed in human glaucoma as well (see Section 6.1), indicating that oxidative stress may contribute to the complement dysregulation observed in glaucoma." (PMID 38396986, 2024). "As a proof of concept, the use of a five-protein panel, consisting of C4a, CFH, FCN3, APOA4, and TTR predicts the transition to glaucoma disease in 78% of cases." (PMID 32585848, 2020). "However, eight proteins (C6, C8G, CFH, C3, CFHR1, CFI, CLU, and SERPING1) were significantly downregulated in Caucasian glaucoma subjects." (PMID 37763167, 2023). "Moreover, the five-protein panel, consisting of C4a, CFH, FCN3, APOA4, and TTR, predicted the transition to glaucoma in 78% of cases and correctly classified 89% of cases with advanced glaucoma in this animal model." (PMID 32585848, 2020). "The proteins ITIH4 and CFH were found in higher concentrations in 10 and 14 month old glaucomatous mice (DBA/2J_G10 and DBA/2J_G14) compared to preglaucomatous stage (DBA/2J_G4), therefore suggesting changes in the transition phase to glaucoma." (PMID 32585848, 2020).
ovarian carcinoma (8 papers, 2002 to 2025). A malignant neoplasm originating from the surface ovarian epithelium. "Complement 7 (C7) and complement factor H (CFH), both of which are components of the complement system, have previously been identified as potent indicators of complement activation in endometriosis and endometriosis-associated ovarian cancer." (PMID 36339397, 2022). "Out of larger subset of candidate biomarker proteins our studies identified, TMEM205 and CFH were found to have the most prominent and consistently increased expression in platinum-resistant ovarian cancer." (PMID 40210758, 2025). "circ-CFH (circ_0015756) is derived from the complement factor H (CFH) gene and locates on chr1 (196706604-196712758), which has been suggested to function as a tumor promoter in ovarian cancer, glioma, and hepatocellular carcinoma." (PMID 35415236, 2022). "Furthermore, ascitic fluid taken from ovarian cancer patients showed surface deposition of C3 with increased CFH (which is only mildly overexpressed in these cells in our dataset)." (PMID 30383866, 2018). "However, previous research indicates that CFH plays a crucial role in the development and progression of various tumors, such as ovarian cancer and non-small cell lung cancer, where changes in CFH expression are closely related to disease severity, prognosis, and survival rate." (PMID 38549939, 2024). "Moreover, the decreased sialylation levels of CLUS, CFH, and HEMO in serum of ovarian cancer patients were validated which showed that these biomarkers have potential utility for diagnosis of ovarian cancer with high accuracy." (PMID 29680984, 2018).
atherosclerosis (7 papers, 2008 to 2024). A disease characterized by the build-up of fatty material and calcium deposition in the arterial wall resulting in partial or complete occlusion of the arterial lumen. "In a murine model of atherosclerosis, CFH deficiency has been shown to limit plaque necrosis in a manner dependent on complement C3." (PMID 39660125, 2024). "The eFH moderate risk group demonstrates almost identical prevalence of atherosclerosis as the cFH positive group (corresponding to the eFH high-risk group)." (PMID 23658806, 2013). "The most important modulators of CFH binding to MDA-epitopes – the CFH variant Tyr402His and the deletion of CFHR3&CFHR1 genes – are frequent in the population and affect the development of the two most common diseases, atherosclerosis and AMD." (PMID 36248824, 2022). "Deletion of CFHR3&CFHR1 genes offers protection in both of them, while Tyr402His is deleterious in AMD and possibly atherosclerosis, highlighting CFH’s importance in homeostatic responses." (PMID 36248824, 2022). "Cell-autonomous regulation of complement component C3 by complement factor H (CFH) modulates macrophage efferocytosis and impacts the progression of atherosclerosis." (PMID 39660125, 2024).
cutaneous squamous cell carcinoma (7 papers, 2015 to 2025). "Further, CFH levels are elevated in cutaneous squamous cell carcinoma and overexpression is linked to immunosuppression." (PMID 38389705, 2024). "In cutaneous squamous cell carcinoma (sCC), increased tumor tissue expression of CFH has been observed and suggested as a potential biomarker." (PMID 40283026, 2025). "In this study, we measured the blood levels of a protein called complement factor H in patients with different stages of cutaneous squamous cell carcinoma." (PMID 40647461, 2025). "This study identifies serum CFH as a promising biomarker of disease progression and immunotherapy response in cutaneous squamous cell carcinoma." (PMID 40647461, 2025). "Among the 10 IFN-γ-related genes, for instance, the increased expression of CFH interferes with proper immune surveillance and decreases the effectiveness of the immune response, thus promoting cutaneous squamous cell carcinoma progression." (PMID 35747790, 2022). "In cSCC (cutaneous squamous cell carcinoma) complement factor H and factor H-like protein-1 have been identified as potential progression markers as their gene expression was upregulated in cSCC cell lines and primary cSCC tumors." (PMID 29423024, 2018). "Our results suggest that complement factor H may serve as a simple blood-based marker to identify patients with aggressive cutaneous squamous cell carcinoma earlier." (PMID 40647461, 2025). "Since then, several reports have confirmed the role of CFH in various solid tumors including glioblastoma, bone cancer, ovarian cancer, colon cancer, cutaneous squamous cell carcinoma and breast cancer." (PMID 38389705, 2024). "Furthermore, increased CFH expression is associated with increased prevalence of Tregs and an immunosuppressive TME in cutaneous squamous cell carcinoma." (PMID 38389705, 2024). "Additionally, CFH may function as a prognostic biomarker in other malignancies including cutaneous squamous cell carcinoma." (PMID 38389705, 2024). "Its prognostic value in CRC may be related to recent reports, where complement factor H was found to be highly expressed in cutaneous squamous cell carcinoma (cSCC) and non-small cell lung cancer (NSCLC) cells, and where it was associated with progression in cSCC and prognosis in NSCLC." (PMID 26253080, 2015).
glioma (7 papers, 2002 to 2025). A benign or malignant brain and spinal cord tumor that arises from glial cells (astrocytes, oligodendrocytes, ependymal cells). "Circ-CFH expression was found to be greatly increased in glioma tissue and was found to be associated with tumor grade." (PMID 35883576, 2022). "In this study, we investigated the impact of complement factor H (FH) on Tregs within the glioma microenvironment and found that FH is an ICOS ligand." (PMID 39378431, 2025). "Our study allowed us to identify the four-gene signature (CFH, GALNT3, SMC4, and VAV3) associated with the overall survival of glioma TCGA-LGG patients." (PMID 36539408, 2022). "Moreover, comparative analysis of the transcriptome program of the ICD-based DC vaccine with transcriptome data from the TCGA-LGG dataset identified a four-gene signature (CFH, GALNT3, SMC4, VAV3) associated with overall survival of glioma patients." (PMID 36539408, 2022). "Circ-CFH expression was also significantly increased in U251 and U373 glioma cell lines." (PMID 35883576, 2022). "Circ-CFH promotes glioma growth via miR-149 sponging and AKT1 signaling pathway regulation." (PMID 35883576, 2022). "Meanwhile, Circ-CFH was significantly upregulated in glioma tissue and was positively correlated with tumor grade, and it markedly increased the proliferative ability of glioma cells by specifically sponging miR-149 and releasing AKT1." (PMID 32061256, 2020). "This study identifies complement factor H as a ligand for the immune checkpoint molecule ICOS, which impacts Treg function in glioma." (PMID 39378431, 2025).
lung adenocarcinoma (7 papers, 2014 to 2023). A carcinoma that arises from the lung and is characterized by the presence of malignant glandular epithelial cells. "Tumor cells also use CFH to evade destruction by complement and a high level of CFH on tumors is associated with poor survival in lung adenocarcinoma." (PMID 34133431, 2021). "CFH (complement factor H) might be a novel diagnostic marker for human lung adenocarcinoma." (PMID 24516561, 2014). "Complement factor H has been reported to be a component of the proteome of EVs isolated from the plasma of lung adenocarcinoma patients and from highly metastatic hepatocellular carcinoma (HCC) cell lines." (PMID 34133431, 2021). "The ToppFun FEA, relative to diseases, predicted a possible association of the RAC1, CFH and 5 of the 14-3-3 protein family genes, namely SFN, YWHAB, YWHAE, YWHAG and YWHAZ with lung adenocarcinoma." (PMID 35366267, 2021). "The concentration of ceruloplasmin was reduced by approximately three orders of magnitude in patients with neurological disorders compared to healthy volunteers, and those of gelsolin isoform 1 and complement factor H were abruptly reduced in patients with lung adenocarcinoma." (PMID 36614211, 2023). "In another research, an EV protein component, complement factor H (CFH), isolated from the plasma of lung adenocarcinoma patients and highly metastatic hepatocellular carcinoma (HCC), was also shown to be active in tumor cell-derived EVs and protect them from complement lysis and phagocytosis." (PMID 36297672, 2022).